PSG8 (pregnancy specific beta-1-glycoprotein 8)
Tractability: Antibody: UniProt places it where antibodies can reach, with high confidence; UniProt predicts a signal peptide or a membrane-spanning region; its Gene Ontology location is reachable by antibodies, with medium confidence.
Gene: Protein-coding gene on chromosome 19 (42,752,686 to 42,765,678, reverse strand). Ensembl gene ENSG00000124467.
Subcellular location: Secreted
Pathways (Reactome):
Hemostasis: Cell surface interactions at the vascular wall
Gene Ontology:
Cellular component: extracellular region
Genetic constraint (gnomAD): Loss-of-function variants: 57 observed, 41.56 expected, observed/expected ratio (o/e) 1.37, 90% interval 1.11 to 1.71. The synonymous counts are far from expectation, so gnomAD's model fits this gene poorly and the ratio says little. Missense variants: 783 observed, 521.83 expected, observed/expected ratio (o/e) 1.5, 90% interval 1.41 to 1.59. Synonymous variants: 280 observed, 197.28 expected, observed/expected ratio (o/e) 1.42, 90% interval 1.29 to 1.57.
Homologues: Paralogues in human: PSG1 (91% identical), PSG3 (89% identical), PSG7 (89% identical), PSG4 (88% identical), PSG6 (87% identical), PSG9 (85% identical), PSG5 (67% identical), PSG2 (66% identical), PSG11 (65% identical), CEACAM1 (43% identical), CEACAM5 (39% identical), CEACAM8 (38% identical), and 12 more.
Diseases named in the same sentence as PSG8 in open-access papers:
PSG8 is named in the same sentence as 5 diseases in open-access papers, as found by Europe PMC text mining. Sharing a sentence is not in itself a finding about the gene and the disease. The quoted sentences say what the papers report.
kidney cancer (1 paper, 2025). Primary or metastatic malignant neoplasm involving the kidney. "The signature of PSG3, PSG7, and PSG8 was also found to show a statistically significant survival difference (P = .0138) between the PSG+ and PSG− groups in uterine cancer and borderline significance (P = .0746) in female kidney cancer patients." (PMID 40257008, 2025).
cancer (1 paper, 2025). A tumor composed of atypical neoplastic, often pleomorphic cells that invade other tissues. "We then asked if this pattern (a statistically significant alteration of the ‘KRAS Signaling Down’ pathway between the PSG+ and PSG− groups in female LUAD patients grouped by the signature of PSG3, PSG7, and PSG8) is present in other TCGA cancer datasets." (PMID 40257008, 2025). "The signature of PSG3, PSG7, and PSG8 was further assessed for female patients in other TCGA cancer datasets." (PMID 40257008, 2025).
tumor (1 paper, 2025). "Note that a tumor sample in which PSG3, PSG7, and PSG8 had no expression was defined as PSG− and otherwise was defined as PSG+." (PMID 40257008, 2025).
PSG8 also shares sentences with these, for which no sentence is quoted: Miscarriage (1 paper); uterine cancer (1).